RN7SKP111 (RN7SK pseudogene 111)
Gene: Miscellaneous RNA gene on chromosome 20 (11,818,821 to 11,819,091, reverse strand). Ensembl gene ENSG00000222281.
Homologues: Orthologues: chimpanzee 7SK (97% identical). Paralogues in human: RN7SKP9 (82% identical), RN7SKP255 (82% identical), RN7SKP71 (82% identical), 7SK (81% identical), RN7SKP176 (81% identical), RN7SKP203 (81% identical), RN7SKP133 (80% identical), RN7SKP45 (80% identical), RN7SKP90 (80% identical), RN7SKP131 (80% identical), RN7SKP180 (80% identical), RN7SKP37 (80% identical), and 284 more.